CD44 (CD44 molecule (IN blood group))
Diseases named in the same sentence as CD44 in open-access papers (continued):
Sharing a sentence is not in itself a finding about the gene and the disease.
tumor (continued). "The first preclinical study of miR-34a in PCa was back in 2011, when our group demonstrated that systemic delivery of miR-34a reduced tumor burden and lung metastasis by targeting CD44 in orthotopic PC-3 and LAPC9 xenografts." (PMID 36139695, 2022). "CD44+ cells obtained from prostate transplantation tumor have tumorigenicity, clonogenic capacity, and metastatic potential." (PMID 35342431, 2022). "A possible positive effect of SIRT in CCA patients is supported by the assessment of CD24 and CD44 that can be expressed by tumor cells and play an important role in their adhesion, survival and growth." (PMID 35954154, 2022). "Directed by external magnetic field and in-structure Fe3O4, DBMN-T was recruited to solid tumor where HA bond with the highly expressed CD44 on tumor cells (Secondary Linking), facilitating the recognition and effector-killing of tumor cells." (PMID 35672752, 2022). "HA receptors are overexpressed in tumor cells, which include a group of cluster of differentiation 44 (CD44) receptors and the receptor for hyaluronic-acid-mediated motility (RHAMM)." (PMID 36421127, 2022). "Due to transformation of the dimerization and localization, more signaling pathways by other bilayer/protein stimulators seem indispensable for CD44 in mediating cell proliferation and tumor progression." (PMID 35733341, 2022). "To determine if the PKD1 pathway was associated with CSCs in pNETs, we further observed the expression of PKD1 and CD44 in tumor tissues from human pNET patients." (PMID 36497140, 2022). "Among them, two xenografts (CD36, CD44) were sacrificed before P2 (Covid19 pandemic period) but after reimplantation, a tumor growing on one passage was noted." (PMID 35326637, 2022). "CD44 and EpCAM peptide-loaded DCs vaccines were also evidenced to endow dramatic anti-tumor immunity to HCC cells." (PMID 36293184, 2022). "Meanwhile, an obvious decrease in the uptake of HZ@GD was found in B16‐F10 cells pretreated with anti‐CD44 antibody than that in PIG1 cells, suggesting that CD44‐mediated actively targeting mechanism facilitates the uptake of HZ@GD for tumor cells." (PMID 34913610, 2022). "Generally, CSCs have surface markers that differ from those of tumor cells, such as Nanog, CD44, SOX2, and OCT4." (PMID 36245214, 2022). "Of note, CD44 is also expressed by a wide range of immune cells that reside in HNSCCs as infiltrates and are also part of the tumor stroma." (PMID 35215208, 2022). "In agreement with the in vitro findings, SB3 overexpression in MONSB3+ and SPH‐derived tumours was associated with an increase in NOTCH, MMP9 and the CSC‐related marker CD44 expression, at the protein level." (PMID 34478594, 2022). "Modulating the levels of CD44 at the cell surface in cancer cells is thus of great importance for disrupting the signaling pathways that favor tumor progression." (PMID 35328491, 2022). "Our previous work demonstrated that CD44 mediates tumor cell aggregation and CTC cluster formation that promotes stemness and metastasis, and is associated with reduced progression-free survival." (PMID 36193887, 2022). "Analysis of 2‐year overall survival (OS) showed that CD44 expression (p = 0.02), tumor size (p = 0.001), lymph node status (p < 0.001), stage (p < 0.001), and grade (p = 0.007) were significantly associated with OS." (PMID 35274800, 2022). "In G3 patients, CgA, CD56, Ki-67, CD24, CD44 and laminin were highly expressed in tumour tissue relative to that in non-tumour tissue with the exception of CD24 for one patient." (PMID 36362433, 2022). "In summary, we show here that Juglone and KPT6566 inhibit the tumorigenic potential of CD44+CD133+ tumor-initiating Caco-2 cells." (PMID 35433695, 2022). "For further analysis, the GlioVis database showed increased mRNA expression levels of CCNB1/CDC42/MAPK7/CD44 oncogenes in GBM tissues compared to non-tumor tissues." (PMID 35008426, 2022).
tumor (continued). "CD44 is a HA receptor that is overexpressed in a variety of tumor cells and acts as a characteristic tumor marker." (PMID 36145550, 2022). "The overexpression of CD44 in this tumor is an early event during the onset of carcinogenesis, which is responsible for the acquisition of a phenotype resistant to senescence and the accumulation of mutations by the transforming hepatocytes." (PMID 35454809, 2022). "CD44 is a cancer stem cell marker, in addition to being associated with cancer progression and being involved in an EMT-like process in tumor cells." (PMID 35982951, 2022). "As few as 100 cells with this phenotype had the ability to form tumours in mice, comprising phenotypically diverse mixed populations of nontumorigenic cells present in the initial tumour as well as additional CD44+/CD24− tumorigenic cells." (PMID 36077812, 2022). "To initially investigate the fate of different CD8 T cell populations after tumor entry, we assessed the expression of CD44 vs. CD62L amongst Kaede Green+ and Kaede Red+ CD8 T cells at 24 and 72 h after photoconversion." (PMID 35472220, 2022). "CD44 mediates resistance to lenalidomide in MM, and CD44-targeted T cells mediate potent anti-tumour effects against MM." (PMID 36315425, 2022). "Silencing of the CD44-regulatory gene with siRNA resulted in tumor shrinkage in a mouse model of OC." (PMID 35269636, 2022). "Hyaluronic acid (HA), a natural polysaccharide that binds explicitly to overexpressed CD44 in tumor tissues, has been widely used as a tumor-targeting agent due to its high compatibility and biodegradability." (PMID 36297527, 2022). "Among these MT-MMPs, MT-MMP-1 is most commonly overexpressed in malignant tumor tissues and interacts with CD44 to stimulate the invasive ability." (PMID 35744840, 2022). "Initially, 93 proteins were found, and up to 30 overexpressed were selected, and CD44, S100A7, and S100P were significantly associated as putative candidates for the early phase of tumor progression." (PMID 36412636, 2022). "The paradigm of early metastasis is featured in a small proportion of primary tumor cells containing high CD44 and low CD24 stem cell-like features which carry the potential to leave the primary tumor early to metastasize at distant sites." (PMID 35736645, 2022). "The authors showed that in the tumor mass obtained from HCT116-CSCs stably transfected with shRNA-CD44, CD44 expression was significantly reduced and this resulted in an evident down-regulation of tumor growth." (PMID 36297407, 2022). "CD44 staining was seen as membranous staining in the tumor cells, and in some cases, there were many cells, likely inflammatory, within the stroma that were positive for CD44." (PMID 36230997, 2022). "The enhanced cellular internalization of HDDA was possibly attributed to the tumor cell-targeting capacity of HA since it can actively target the CD44-overexpressed tumor cells." (PMID 36319625, 2022). "At present, tumor suppression therapy targeting CD44 can inhibit tumor angiogenesis and cell metastasis, and protect cells from ROS damage by activating downstream MAPK signals." (PMID 35501667, 2022). "Since CD44 knockdown was found to suppress HCT116‐CSCs migration and invasion in vitro, xenograft tumor growth assay was performed to examine the effects of CD44 knockdown on in vivo tumorigenicity and metastasis in nude mice." (PMID 35229451, 2022). "The enhanced antitumor activity was most likely due to the targeted delivery of DOX–CDC-H to the tumor site via CD44 targeting and the efficient aggregation of CDC-H nanoparticles for passive targeting, in agreement with the previous results from MTT." (PMID 36365242, 2022). "Among the potential PTX3 receptors, CD44 was the focus because of its confirmed involvement in tumour recurrence, mortality, metastasis and invasion in malignant cancers." (PMID 35090088, 2022). "In particular, it binds cluster determinant 44 (CD44), an adhesion molecule that is highly expressed in a variety of tumor cells." (PMID 35456552, 2022).
tumor (continued). "Subsequently, immunohistochemical (IHC) results showed that compared with the NC group, the expression of Ki67 (proliferation marker) and CD44 (invasion marker) in tumor tissue sections was lower in the TMSB10 knockdown group." (PMID 36163046, 2022). "The majority of IFNγ+ cells were CD44+CD62Lneg and were similar per g tumor in isotype and NK depleted mice." (PMID 36531040, 2022). "Accumulating evidence indicates that the dysregulation of the CD44-Stat3 axis is involved in tumor progression, invasion, metastasis and therapeutic resistance." (PMID 36678534, 2022). "CD44 expression was increased in the invasive front of the tissue and was present in all poorly differentiated tumours." (PMID 35296132, 2022). "Their mesenchymal and stem-like characteristics together with cytoskeletal features and migratory capacity corresponded to the CD44+ tumor cells’ enrichment in the metastatic lymph nodes." (PMID 34228218, 2022). "The experimental results showed that the combination inhibited the proliferation of tumor cells and reduced the number of CD44-positive CSCs." (PMID 36182897, 2022). "The interaction of CD44 and its ligand, hyaluronan, is complex and is thought to play a role in tumor progression." (PMID 35931675, 2022). "There have been controversies about the significance of CD44 expression in NB, and its relationship with tumor progression." (PMID 35457141, 2022). "Forced expression of miR-506 or miR-150 significantly increased the susceptibility of Leptin+ cells to palbociclib treatment by inhibiting colony and tumor spheroid formation, and CD44 expression in Panc-1 and MiaPaCa-2 cells." (PMID 37529006, 2022). "We also found that EerI reversed the positive effects of CD44 on PC and provided a new strategy for the development of anti-tumor drugs." (PMID 35941702, 2022). "CD44 is a well-studied tumour stem cell marker, and it has been confirmed that there is an interaction between the opposite genes and CD44." (PMID 36316684, 2022). "It was also shown that cancer cells with CD44 overexpression were more efficient than normal cells to internalize HA, supporting the feasibility of tumor-specific drug delivery employing HA as the targeting ligand." (PMID 36231028, 2022). "It has been evidenced that CD44 gene knockout can inhibit tumor growth, invasion, and metastasis and also can increase the sensibility of chemotherapeutics." (PMID 35402279, 2022). "The transmembrane glycoprotein receptor CD44 is the major hyaluronan (HA) receptor, and the binding of CD44 to HA has been reported to modulate several phenotypic behaviors in cancer cells, including tumor progression, metastasis, and proliferation." (PMID 35164326, 2022). "Several markers, including aldehyde dehydrogenase (ALDH), octamer-binding transcription factor (OCT4), and CD44, have been shown to identify tumor stem cells in various types of tumors." (PMID 35626430, 2022). "Exosomes liberated from the tumor are able to transfer CD44 protein into mesothelial cells stimulating metalloproteinase-9 (MMP-9) expression, which supports cell homing and invasion." (PMID 35269636, 2022). "The complex is internalized by CD44-based endocytosis upon arrival in the tumor tissue, and the internalized complex rapidly releases cisplatin in the acidic lysosomal compartment." (PMID 36324675, 2022). "Significant reduction in the extravasation of tumor cells was achieved by targeting the hyaluronic acid-CD44 glycocalyx complex." (PMID 35158914, 2022). "We used in vivo limiting dilution assays with a serial dilution of PFK158/control-pretreated ALDH+CD44+ SKOV3 cells to determine the effect of PFK158 on tumor-initiating properties." (PMID 35155224, 2022). "For example, NNMT can alter H2K27 methylation status, affecting m6A of CD44, consequently contributing to the formation of CD44v3, which is closely related to tumor metastasis." (PMID 35756670, 2022).
tumor (continued). "CD44 can also mediate tumor proliferation and immune evasion by promoting PD-L1 expression on the tumor cell surface." (PMID 35719973, 2022). "Correspondingly, the expression of tumor stem cell markers (CD44, CD133, and OCT4) upregulated by miR-4800-3p was also decreased by the overexpression of STK25 in HepB3 and LM3 cells." (PMID 35756606, 2022). "These phenotypic features of GBM on MRI completely coincided with the degree of CD44 expression in the tumor tissues (P/C ratio)." (PMID 35624954, 2022). "Our current data show that two potent chemical Pin1 inhibitors, Juglone and KPT6566, induce apoptotic cell death and inhibit the tumorigenicity of CD44+CD133+ tumor-initiating Caco-2 CRC cells." (PMID 35433695, 2022). "Other Wnt target genes, including matrilysin, CD44, and the urokinase-type plasminogen activator receptor, appear to be more involved in tumor promotion than in tumor initiation." (PMID 35883434, 2022). "Nonetheless, dysregulation of CD44 expression alters the early proliferative status and adhesive properties of tumor cells." (PMID 36428690, 2022). "Merlin-ERM (ezrin-radixin-moesin) family of proteins, acts as a tumor suppressor by inhibiting the CD44-HA signaling." (PMID 35785191, 2022). "In contrast, the ratio of CD44/CD24 expressed on CTRL tumor tissue was significantly high compared to the GEM group." (PMID 35892853, 2022). "We confirmed the decrease in CD44 membrane fraction by performing FACS (fluorescence-activated cell sorting) analysis of catulin control and deficient tumor cells." (PMID 35879327, 2022). "A large endocytic receptor LRP-1 mediated internalization of CD44, which plays an important role in the adhesive properties of tumor cells." (PMID 35024436, 2022). "CD44 is an important cancer stem cell marker in tumors and implicates in malignant processes including cell motility, tumor growth, and angiogenesis." (PMID 35422048, 2022). "Tumor cells overexpress the CD44, LYVE-1 receptors, which are HA-binding receptors, and low expression was also seen in the surface of epithelial hematopoietic and neural cells." (PMID 35267773, 2022). "The protein levels of pAkt and CD44/CD24 in tumor cells were tested with immunohistochemistry analysis." (PMID 35053979, 2022). "It is notable that zebrafish PDX models derived using CD44 enriched cell populations increased tumour burden in both the vehicle control as well as HA-CPNs, and over a 6-day time course the effects of CPNs were reduced in efficacy at later time points." (PMID 35840697, 2022). "Immunohistochemical analysis of tumor xenografts showed that dinaciclib potently lowered the expression of CD44 and Rad51 in SAM68 down-regulated cells." (PMID 35217791, 2022). "In our present study, CLEC1B was significantly negatively correlated with the expression of tumor stemness marker CD44, and its expression was significantly reduced under hypoxic culture conditions in Hep3B and Huh7 cells." (PMID 36307751, 2022). "Jin and colleagues observed in tumor tissue samples that GSCs with PN signal (Sox2+ and Olig2+) were located in perivascular niches, while GSCs with Mes signal (CD44+ and YKL40+) occupied exclusively hypoxic/necrotic regions." (PMID 35205179, 2022). "CD44-expressing cells were shown to escape exogenous DNA damage from radiation-induced double-stranded breaks (DSBs); it ultimately promoted tumor recurrence and resistance to radiation." (PMID 35008426, 2022). "Hyaluronan–CD44 interactions have been shown to be pivotal in various aspects of tumor progression, such as proliferation, migration, invasion, survival, and stemness." (PMID 35954411, 2022). "Targeted delivery of the system to the CD44-overexpressing tumor cells was confirmed by its NIR-induced photothermal property." (PMID 36421127, 2022). "The CD44 expression pattern was consistent among all organoid‐tumor pairs except UTUC‐11 whose organoids lost CD44 expression during culture." (PMID 34914855, 2022).
tumor (continued). "The role of CD44 in tumor progression and particularly in the processes of invasion and metastasis has been well established in many cancers mainly of epithelial origin, which have been the subject of excellent reviews." (PMID 35785191, 2022). "In conclusion, inhibition of tumor progression by modulating CD44 sialylation appears to be a viable option." (PMID 35936713, 2022). "It has been reported that CD44 overexpression, in particular CD44v, contributes to tumor radioresistance through the protection against ROS by stimulating the synthesis of reduced glutathione (GSH) level, a primary intracellular antioxidant." (PMID 36362359, 2022). "CD81 is coexpressed along with CD44 in human circulating tumor cells (CTCs) and enriched in clustered CTCs that promote cancer stemness and metastasis, supporting the clinical significance of CD81 in association with patient outcomes." (PMID 36193887, 2022). "In order to verify the relationship between MAGE-A3 and tumor stemness regulation, we also detected the expression of tumor stem cell markers CD44 and EpCAM in these tissues." (PMID 36367777, 2022). "CD44 not only is involved in the pathogenesis of UC but also can serve as a predictor of tumor development and a therapeutic target." (PMID 36310619, 2022). "After overexpression of CELF2, the expression of CD44s was significantly decreased by AS of the CD44 pre-mRNA, and different key spliceosomes were formed, which inhibited tumor progression." (PMID 35941702, 2022). "The results revealed that SALB reversed chemotherapy resistance to 5-FU and oxaliplatin and inhibited tumor growth by suppressing the expression of stemness markers, such as CD44, CD133, and the transcription factor sox-2 (SOX2)." (PMID 36172536, 2022). "The other method involved sorting the top 5% brightest staining cells with stem cell markers (ALDH and CD44) by FACS, on the basis of our recent findings that ALDH+CD44+ cells isolated from ascites-derived tumor cells show enhanced CSC properties." (PMID 35155224, 2022). "PFK158-pretreated ALDH+CD44+ cells formed smaller tumors, and the tumor formation time was prolonged from an average of 9.4 days to 17.4 days." (PMID 35155224, 2022). "By profiling isogenic cells, CD44 on tumor cells was identified as a negative regulator of “in-cell killing” via inhibiting CIC formation." (PMID 35436988, 2022). "While the normal isoform of CD44 is expressed ubiquitously in both normal adult and fetal tissue, certain splice-isoforms of CD44 are relatively tumor-restricted." (PMID 36605213, 2022). "Along with tumor cells dedifferentiation, the expression of WNT target genes (e.g., Lgr5 and Cd44) associated with 'stem-like' colon cancer cells were remarkably elevated in tumor organoids." (PMID 35541903, 2022). "Together with the afore-demonstrated results, we proposed that CD44 was a potential target for tumor immune therapy through in-cell killing." (PMID 35436988, 2022). "Some specific markers on the surface of various cancer cells, such as epithelial cell adhesion molecule (EpCAM) and type I transmembrane glycoprotein CD44, can be used for cell membrane targeting in tumor PDIT." (PMID 35910806, 2022). "The hyaluronic acid receptor CD44 is a cancer stem cell marker involved in multiple regulation of almost all cancer types, such as cell survival, proliferation, motility, and tumor microenvironment remodeling." (PMID 36292918, 2022). "CD24 and CD44 expression has been described in tumors before, and they are involved in tumor survival and growth." (PMID 35954154, 2022). "An interesting observation in our data set was a significant number of the floor of the mouth tumours having high CD44 positivity." (PMID 35296132, 2022). "CD44, a cell-adhesion molecule has a dual role in tumor growth and progression; it acts as a tumor suppressor as well as a tumor promoter." (PMID 35164076, 2022).